SMARCC2 (SWI/SNF related BAF chromatin remodeling complex subunit C2)
Diseases named in the same sentence as SMARCC2 in open-access papers (continued):
Sharing a sentence is not in itself a finding about the gene and the disease.
cancer (14 papers, 2016 to 2024). A tumor composed of atypical neoplastic, often pleomorphic cells that invade other tissues. "Interestingly, with INI1 than that of the other two core subunits encoding the SWI/SNF complex (BAF155/SMARCC1 and BAF170/SMARCC2), which are rarely mutated in human cancers, suggesting that mutations in IN1 increase the risk of cancer in individuals." (PMID 36883311, 2023). "Since the differentiation of mESCs leads to the expression of SMARCC2, both SMARCC1 and SMARCC2 are proteolyzed in mouse embryonic fibroblasts and various cancer cells." (PMID 38396925, 2024). "To summarize, SMARCC2 needs more investigation as a potential cancer driver gene." (PMID 37516822, 2023).
tumor (12 papers, 2016 to 2025). "Steady transfection of SMARCC2 led to decrease in volume, weight, proliferative index, microvessel density and M2 macrophage accumulation of subcutaneous tumours produced by IMR‐32 cells in immune‐deficient mice, and these effects were eliminated by transfection of CNBP." (PMID 37186134, 2023). "Subsequent cell function experiments also demonstrated the tumor suppressor function of SMARCC2 subunits in GBM cell lines." (PMID 36418306, 2022). "In addition, CNBP repressed the SMARCC2 activity to facilitate rRNA processing and ribosome biogenesis of tumour cells, leading to increase of M2 macrophage polarization." (PMID 37186134, 2023). "This work broadens current literature regarding the functions of SWI/SNF subunits in controlling ribosome biogenesis, and suggests that KPNB1/CNBP/SMARCC2 axis‐mediated ribosome biogenesis and M2 macrophage polarization is a valuable therapeutic target for tumours." (PMID 37186134, 2023). "In contrast, downregulation of SMARCC2 significantly increased tumor volume." (PMID 36418306, 2022). "Taken together, these observations suggest that SMARCC2 may act as a tumor suppressor in GBM along with other epigenetic factors." (PMID 36418306, 2022). "Additional investigation is necessary to elucidate the therapeutic effects of targeting CNBP/SMARCC2 in TH‐MYCN transgenic or immunocompetent mice, while quantitative proteomics are helpful in exploring additional CNBP protein partners in tumour progression." (PMID 37186134, 2023). "Clinical NB cases with up‐regulation of KPNB1, CNBP, SMARCC1, SMARCA4 or down‐regulation of SMARCC2 have poor survival and prognosis, indicating KPNB1/CNBP/SMARCC2 axis as a valuable target for therapeutics of tumours." (PMID 37186134, 2023). "Since immunohistochemical staining revealed the enrichment of F4/80+ M2 macrophages in subcutaneous xenograft tumours formed by CNBP over‐expressing NB cells, the impacts of CNBP or SMARCC2 on interplay between NB and macrophages were further explored." (PMID 37186134, 2023). "The assembly of the subcomplex comprising SMARCB1 and SMARCC2 and/or SMARCC1 is essential for the tumor-suppression function of SMARCB1." (PMID 33024572, 2020). "Interestingly, FBXO28 is found to exert either oncogenic or tumor suppressing functions by targeting MYC, SMARCC2 or HIF-1α, under different cellular contexts, complicating its role in tumorigenesis and metastasis." (PMID 37596321, 2023). "We observed in our study that the PI3K–AKT pathway was significantly inhibited when SMARCC2 was overexpressed; however, the PI3K–AKT promoter SC79 only partially reversed these tumor suppressor effects, suggesting that other epigenetic factors may be involved." (PMID 36418306, 2022). "Furthermore, SMARCC2 exhibited diminished expression in tumor tissue, with a negative correlation to TRIM37 levels." (PMID 39349442, 2024).
neurodevelopmental disorder (4 papers, 2021 to 2026). A behavioral and cognitive disorder with onset during the developmental period that involves impaired or aberrant development of intellectual, motor, or social functions. "In the present study, two de novo variants (c.1311‐3C>G, c.347G>A (p.Arg116His)) and a novel de novo variant (c.346C>T (p.Arg116Cys)) in the SMARCC2 gene were detected in three patients with neurodevelopmental disorders by whole exome sequencing." (PMID 41532374, 2026). "The BAF complex is primarily composed of ARID1A, ARID1B, SMARCA4, SMARCB1, SMARCE1, and SMARCC2, and heterozygous variant in either of them can lead to several distinct neurodevelopmental disorders (NDDs) with overlapping phenotypes, termed BAFopathies." (PMID 39901255, 2025).
neurodegenerative disease (1 paper, 2024). A disorder of the central nervous system characterized by gradual and progressive loss of neural tissue and neurologic function. "Due to the similarities with aggregate pathology observed in other neurodegenerative diseases, we investigated potential interactions between SMARCC2+ cytobodies and α-Syn and p62." (PMID 39689145, 2024). "Our data does not preclude the presence of truncated SMARCC2 from the nucleus, which still contains the SWIRM domain, but does add to the complex role of SMARCC2 in chromatin regulation and neurodegenerative diseases such as PD." (PMID 39689145, 2024).
SMARCC2 also shares sentences with these, for which no sentence is quoted: pancreatic cancer (3 papers); infection (2); Intellectual disability (2); malignant rhabdoid tumors (2); neurologic disorders (2); small cell lung carcinoma (2); Tetralogy of Fallot (2); allergic purpura (1); Anxiety (1); attention deficit-hyperactivity disorder (1); cryptorchidism (1); diabetes (1); drug allergies (1); eczema (1); endometrioid carcinoma (1); epithelioid sarcoma (1); hepatocellular carcinoma (1); hypoplastic left heart syndrome (1); Kleefstra syndrome (1); macular degeneration (1); medulloblastoma (1); myeloid neoplasm (1); myopia (1); Nicolaides-Baraitser syndrome (1); ovarian clear cell cancer (1); pancreatic undifferentiated carcinoma (1); renal cell carcinoma (1); sarcoma (1); syndromic intellectual disability (1); urothelial carcinoma (1).